SEMA3E (semaphorin 3E)
Diseases named in the same sentence as SEMA3E in open-access papers (continued):
Sharing a sentence is not in itself a finding about the gene and the disease.
pancreatic neuroendocrine carcinoma (1 paper, 2016). "Our discovery that Sema3E was strongly expressed in the nuclei of tumor cells in PDAC, but not in normal acinar cells or tumor cells of pancreatic neuroendocrine carcinoma, could point to Sema3E's potential role as a transcription factor." (PMID 27911862, 2016).
Sepsis (1 paper, 2025). Sepsis is defined as life-threatening organ dysfunction caused by a dysregulated host response to infection. "The other “top genes” induced by sepsis in the spleen encode Semaphorin 3e (Sema3e), Interleukin-17F (Il17f), and Cytotoxic T lymphocyte antigen 4 (Ctla4)." (PMID 41229427, 2025). "Fourth, the identification of the IL-10, Semaphorin 3e, and IL-17F as the top responders to the polymicrobial sepsis that are being suppressed by the NTCI." (PMID 41229427, 2025).
Stroke (1 paper, 2022). Sudden impairment of blood flow to a part of the brain due to occlusion or rupture of an artery to the brain. "In the present study, Sema3E expression was rapidly and precisely induced in peri-infarct area neurons during the early phase after stroke." (PMID 33978913, 2022). "VEGF/VEGFR2 signaling is a master regulatory pathway for vascular development and function in health and disease; therefore, we assumed that Sema3E-Plexin-D1 controlled VEGF signaling after stroke." (PMID 33978913, 2022). "Collectively, future studies should explore the involvement of Sema3E/Plexin-D1 signaling in the pericyte coverage process during vascular remodeling after stroke." (PMID 33978913, 2022). "To investigate whether reactivation of Sema3E/Plexin-D1 signaling following stroke leads to vascular alterations, we first monitored CBF in the ischemic region using laser Doppler imaging." (PMID 33978913, 2022). "Therefore, enhancing Sema3E-Plexin-D1 signaling in angiogenic vessels during the critical period of vascular repair could become a new target for stroke treatment." (PMID 33978913, 2022).
tongue SCC (1 paper, 2019). "It was reported in tongue SCC that the high immunohistochemical expression of vascular endothelial growth factor C (VEGF-C), vascular endothelial growth factor receptor 3 (VEGFR-3), CCR7 and semaphorin 3E (SEMA3E) are predictors of metastasis." (PMID 31011147, 2019).
ulcers (1 paper, 2015). "In SSc, Sema3E levels were significantly increased in patients with early nailfold videocapillaroscopy (NVC) pattern compared to active/late patterns and pRP, and in patients without digital ulcers versus those with ulcers." (PMID 26292963, 2015).
tumor (43 papers, 2008 to 2025). "In contrast to full-length sema3E, p61-Sema3E induces the association of plexin-D1 with ErbB2 and the phosphorylation of ErbB2 and, as a result, induced tumor cell metastasis." (PMID 37627074, 2023). "The therapeutic ability of the uncleavable variant of Sema3E (Uncl-Sema3E) was demonstrated in multiple tumour models where it acts as a novel inhibitor of tumour growth, metastasis, and angiogenesis." (PMID 35983029, 2022). "This is the case of the mutated, uncleavable variant of Sema3E that was validated as a tumor/angiogenesis suppressor following its delivery in tumor or choroidal neovascularization models." (PMID 33858502, 2021). "To investigate the role of Sema3E in mediating invasiveness and/or migratory ability during tumor progression, we performed gain and loss of function studies in OEC cells." (PMID 21559368, 2011). "One CIS, SEMA3E, encodes a neuronal development protein which was recently found to be expressed on tumor cells." (PMID 19148292, 2009). "Indeed, a point-mutated sema3E resistant to cleavage by furin-like pro-protein convertases inhibits angiogenesis and tumor progression but is unable to activate ErbB2 and is unable to promote tumor metastasis." (PMID 30696103, 2019). "Tumor‐related studies reported that Sema3E and its receptor Plexin D1 are significantly upregulated in various cancers such as colon cancer and metastatic breast cancer." (PMID 40112179, 2025). "Plexin-D1 mediates inhibitory signals induced by full-length sema3E to inhibit tumor angiogenesis and tumor metastasis." (PMID 37627074, 2023). "Secondly, SEMA3E induces the nuclear translocation of the Snail2 transcription factor to induce EMT in tumour cells." (PMID 37685898, 2023). "Inflammation contributes greatly to tumorigenesis and tumor development, indicating that SEMA3E potentially accelerates tumor progression by regulating chronic inflammation, which is a hallmark of various malignancies." (PMID 36998443, 2023). "Sema3E acts as a repulsive factor for plexin-D1-expressing endothelial cells, leading to decreased neoangiogenesis and reduced tumor growth." (PMID 36068209, 2022). "SEMA3E is known to act as a repulsive factor for endothelial cells that express plexin-D1, resulting in decreased neoangiogenesis and reduced tumor growth." (PMID 36068209, 2022). "Sema3E is expressed in numerous cell types such as adipocytes, DCs, thymic epithelial cells, macrophages, tumour cells, and osteoblasts." (PMID 35983029, 2022). "Very surprisingly a paradoxical effect was observed by Casazza, being tumor growth inhibited in Sema3E overexpressing tumors, while metastases were induced." (PMID 33858502, 2021). "The impact of Sema3E on tumor angiogenesis is consistent with its recognized important role in the regulation of heart and vessels development." (PMID 33537086, 2021). "The pheonomenon of increased gene expression in cancer tumours while function as tumour suppressor or of decreased gene expression while function as tumor promotor has also been observed for SEMA3E and other genes as well." (PMID 32241267, 2020). "SEMA3E shows tumour promoter role in multiple cancer types such as gastric, breast, and pancreatic cancers." (PMID 32241267, 2020). "Most members showed tumour inhibiting roles while only SEMA3E was found to promote tumour invasion and metastasis." (PMID 32241267, 2020). "Even though little is known about the role of SEMA3E in the regulation of tumor-infiltrating immune cells, suggestions for further investigation came from recent reports addressing its role in inflammatory cells." (PMID 30658382, 2019). "Ectopic over-expression of sema3E in a variety of tumor cell types inhibits tumor development from such cells." (PMID 30696103, 2019). "Semaphorin 3E (Sema3E), originally defined as M-SemaH, was identified in tumor cells and involved in embryonic development." (PMID 30405423, 2018).
tumor (continued). "In contrast to Sema3A tumor suppressor effects, Sema3E, which shares Plexin D1 receptor with Sema4A and Sema4D, consistently demonstrated the pro-tumoral effects." (PMID 30598022, 2018). "Sema3A, Sema3B and Sema3F have been long considered inhibitors of tumor growth and metastasis, even if it has been reported that Sema3E inhibits tumor growth but promotes metastasis." (PMID 30454024, 2018). "In contrast, normal canine osteoblasts possessing high basal levels of miR-34a expressed significantly lower levels of KLF4 and SEMA3E compared to OSA tumor samples." (PMID 29293555, 2018). "Sema3E-Plexin D1 interaction promoted tumor growth and metastasis, and this ligand-receptor pair expression correlated positively with metastatic progression of colon, liver, and melanoma cancers." (PMID 30598022, 2018). "In an orthotopic xenograft mouse model generated by the implantation of Mia-S3E and Mia-VCtrl cells into nude mice, we found that Sema3E-overexpressing cells had a higher rate of tumor formation, and also formed bigger tumors compared to Mia-VCtrl." (PMID 27911862, 2016). "One explanation for the contrasting behavior of Sema3E between different types of cancers is the distinct tumor microenvironments of these disparate tumors." (PMID 27911862, 2016). "In an orthotopic mouse xenograft model, Sema3E-overexpressed cells exhibited greater tumor incidence and growth, whereas Sema3E-knockout cells had reduced tumor incidence and growth." (PMID 27911862, 2016). "In the VA Medical Center patient samples, we observed strikingly strong staining of Sema3E in the nuclei of tumor cells compared to mostly cytoplasmic staining in healthy cells." (PMID 27911862, 2016). "There was a statistically significant higher expression of Sema3E transcription in a paired analysis of tumor samples vs. matched controls (p=0.023), indicating that Sema3E is overexpressed in PDAC." (PMID 27911862, 2016). "Semaphorin-3E (Sema3E) is a member of an axon guidance gene family, and has recently been reported to contribute to tumor progression and metastasis." (PMID 27911862, 2016). "Altogether, these results show that overexpression of Sema3E enhanced tumor growth in an orthotopic in vivo setting." (PMID 27911862, 2016). "Conversely, knockout of Sema3E suppressed cancer cell proliferation and migration in vitro, and reduced tumor incidence and size in vivo." (PMID 27911862, 2016). "Semaphorin 3E (Sema3E) is a secreted molecule that controls angiogenesis and tumor cell survival and serves as a ligand for Plexin D1." (PMID 26356073, 2015). "In colorectal cancer and pancreatic cancer, Sema3E expression is inversely correlated with tumor prognosis." (PMID 26036259, 2015). "Axon guidance protein Semaphorin 3E (Sema3E) promotes tumor metastasis and suppresses tumor cell death." (PMID 26036259, 2015). "For instance, a 61KD isoform of Sema3E that is obtained by proteolytic processing by furin increases the invasiveness and distant metastasis of tumor cells." (PMID 26036259, 2015). "It is thus likely that a major part of the anti-tumorigenic effects of sema3D and sema3E is mediated through inhibition of tumor angiogenesis." (PMID 22936999, 2012). "The np2agonist sema3F also inhibited tumor formation effectively although somewhat less effectively than sema3E and sema3D." (PMID 22936999, 2012). "Here too, expression of sema3E and sema3D in the tumor cells significantly prolonged the survival of the mice." (PMID 22936999, 2012). "As in the previous experiment, we found that expression of sema3D or sema3E almost completely inhibited tumor development from cells implanted in the brain cortex of mice (data not shown)." (PMID 22936999, 2012). "Sema3E and sema3D seemed to be the most effective inhibitors and abrogated almost completely tumor development in spite of their marginal effect on cell proliferation in-vitro." (PMID 22936999, 2012).
tumor (continued). "Activation of ErbB2/Neu kinase is also required for pro-invasive/metastatic activity in tumor cells, and we found that ErbB2 transcripts were significantly changed in Sema3E-positive OEC cells in gene profiling via RNA microarray analysis (data not shown)." (PMID 21559368, 2011). "Sema3E binds directly with Plexin-D1 to transduce intracellular signal during embryonic or tumor angiogenesis." (PMID 21559368, 2011). "We report here that Sema3E from tumor cells can act on themselves through Plexin-D1 to induce EMT and concomitantly facilitate cell migration and malignant progression." (PMID 21559368, 2011). "RNAi-mediated knockdown of Sema3E, Plexin-D1 or Snail1 in Sema3E-expressing tumor cells resulted in compromised cell motility, concurrent reversion of EMT and diminished nuclear localization of Snail1." (PMID 21559368, 2011). "In conclusion, we have found for the first time that the semaphorins sema3A, sema3D, sema3E and sema3G possess anti-tumorigenic and anti-angiogenic properties similar to those displayed by the previously identified tumor suppressor sema3F." (PMID 18818766, 2008). "We have presented here for the first time evidence indicating that sema3D, sema3G sema3E and sema3A can significantly reduce the concentration of microvessels in tumors that develop from tumor cells that express these semaphorins." (PMID 18818766, 2008). "Semaphorin 3E (SEMA3E) has also been reported to promote tumour initiation or progression in BC." (PMID 37685898, 2023). "Additionally, it was reported that sema3E induces invasiveness and metastatic spreading of tumor cells through the transactivation of ErbB2 by a post-translationally modified sema3E that was truncated by furin-like pro-protein convertases (P61-sema3E)." (PMID 37627074, 2023). "An inverse correlation between Sema3E and plexinD1 during tumor progression was also evidenced." (PMID 33858502, 2021). "Interestingly, a modified recombinant isoform of Sema3E with inhibitor activity has been successfully applied to suppress angiogenesis and tumor progression in mouse models." (PMID 33537086, 2021). "In a glioblastoma model, ectopic expression of Sema3D or Sema3E reduced tumor growth." (PMID 32210960, 2020). "In summary, our results indicate that SEMA3A, SEMA3C, SEMA3E, and SEMA3F are more often to promote tumorigenesis and associate with poor prognosis, while the other SEMA3s are more often to play a tumour suppressor role and generally associate with better prognosis." (PMID 32241267, 2020). "For example, expression levels of SEMA3E showed the largest inter-tumour heterogeneity with some tumours having very low levels of SEMA3E (ACC, DLBC, HNSC, KIRC, KIRP, AML, and PCPG), while others were characterized with high levels of SEMA3E expression (BRCA, CCA, and GBM)." (PMID 32241267, 2020). "Among them, SEMA3E showed the greatest inter- tumour heterogeneity." (PMID 32241267, 2020). "Notably, some semaphorins such as sema3C and sema3E have also been found to potentiate tumor progression using various mechanisms." (PMID 30696103, 2019). "Although promising, these in vivo findings leave open the question of whether local or systemic administration of the soluble forms of Sema3A, Sema3D, Sema3E, or Sema3F may recapitulate the tumor-suppressing effect of ectopically expressed molecules." (PMID 31052281, 2019). "On the other hand, SEMA3E is also known to restrict vessel development and tumor angiogenesis." (PMID 30658382, 2019). "However, sema3E was also found to function as an inhibitor of angiogenesis, like other class-3 semaphorins, and thus, should function as an inhibitor of tumor metastasis." (PMID 30696103, 2019). "Moreover, the expression of Sema3E in human tumor samples correlates with metastatic progression and in support of these findings, knockdown of Sema3E in human carcinoma cell lines reduced their metastatic potential when injected into mice." (PMID 29293555, 2018).
tumor (continued). "We also showed that Mia-S3E tumors were more vascularized than Mia-VCtrl tumors, indicating that Sema3E overexpression may promote tumor angiogenesis, which in turn promotes greater tumor growth." (PMID 27911862, 2016). "This suggests that in an in vivo setting, Sema3E may also have paracrine effects on endothelial cell growth in the tumor microenvironment." (PMID 27911862, 2016). "Sema3E has also been shown to suppress tumor cell death in metastatic breast cancer." (PMID 26036259, 2015). "On the contrary, in some cancers, up-regulation of Sema3E promotes tumor metastasis." (PMID 26036259, 2015). "For example, as a repulsive cue for Plexin D1-expressing endothelial cells, overexpression of Sema3E inhibits tumor development via the disruption of tumor vascular patterning; similarly, recombinant Sema3E can inhibit PDGF-mediated proliferation and migration of human airway smooth muscle cells." (PMID 26036259, 2015). "SEMA3E overexpression in a tumor xenograft model dramatically decreased the metastatic potential." (PMID 26485755, 2015). "Class-3 semaphorins, such as sema3A, sema3B, sema3F have been previously characterized as natural tumor suppressors and there are indications that sema3E also may function as a natural tumor suppressor." (PMID 22936999, 2012). "By contrast, injection of Sema3E-expressing OEC clones caused metastatic tumor growth in the lung as evidenced by an increase of total lung weight, gross intrapulmonary hemorrhage, and the presence of microscopic tumor nests near the vascular trees." (PMID 21559368, 2011). "In ovarian endometrial carcinomas, we have provided a previously unknown mechanism of Sema3E/Plexin-D1 signaling that facilitates tumor progression through Snail1-medidated EMT." (PMID 21559368, 2011). "However, SEMA3E also has an important role in promoting tumor progression." (PMID 40103807, 2025). "However, Inflammation is a major contributor to tumor progression, suggesting that sema3E may also be able to promote tumor progression by modulation of the chronic inflammation that is a hallmark of many types of tumors." (PMID 30696103, 2019). "SEMA3E was among the common biomarkers significantly up-regulated in their expression after treatment of both cell lines with fisetin that may explain in part the growth inhibitory effect of fisetin on tumor growth." (PMID 28052097, 2017). "Hence, knockout of Sema3E decreased rate of tumor incidence." (PMID 27911862, 2016). "Following the binding of sema3E, the interaction with NR4A1 is disrupted, enabling sema3E-induced tumor cell survival." (PMID 37627074, 2023). "Whereas SEMA3A, SEMA3C, and SEMA3F were mainly up-regulated in the tested tumours, the rest of the members SEMA3B, SEMA3D, SEMA3E and SEMA3G were primarily down-regulated with a few exceptions." (PMID 32241267, 2020). "All other SEMA3 family members show inconsistent up- or down-regulation in different cancer tumours, where SEMA3B, SEMA3D, SEMA3E, and SEMA3G are primarily down-regulated, and SEMA3A and SEMA3C are mainly up-regulated in the tested cancer types." (PMID 32241267, 2020). "RT-qPCR demonstrated that primary canine OSA tumor tissues express high levels of putative miR-34a target genes, KLF4 and SEMA3E." (PMID 29293555, 2018). "The present analysis showed, for the first time, that the anti-tumor effect of fisetin was mediated mainly through activation of CDKN1A, SEMA3E, GADD45B and GADD45A and down-regulation of TOP2A, KIF20A, CCNB2 and CCNB1 genes." (PMID 28052097, 2017). "We also showed that four members of the class 3 semaphorin family were down-regulated by metformin and aspirin, including two pro-tumor semaphorins, SEMA3C and SEMA3E." (PMID 26294325, 2015). "Our results suggest that the acquisition of SEMA3E gene amplification might relate to the metastatic potential in CRC and that CNVs can change during the process of tumor progression." (PMID 30898102, 2019).